MSH6 (mutS homolog 6)
Diseases named in the same sentence as MSH6 in open-access papers (continued):
Sharing a sentence is not in itself a finding about the gene and the disease.
endometrial cancer (continued). "We infected endometrial cancer cells (Ishikawa and HEC-1B) with lentivirus that can knock down or overexpress MSH6 and confirmed its infection effect by RT-qPCR and WB." (PMID 38390329, 2024).
endometrial cancer (continued). "Burden testing identifies 13 cancer genes with significant enrichment of rare truncations, some associated with specific cancers (for example, RAD51C, PALB2 and MSH6 in AML, stomach and endometrial cancers, respectively)." (PMID 26689913, 2015). "To explore the biological functions and pathways that may be affected by changes in MSH6 expression in endometrial cancer, we used R to conduct GO and KEGG analyses on the DEGs upregulated in the MSH6 high and low expression groups, respectively." (PMID 38390329, 2024). "MSH6 is a mismatch-repair gene involved in hereditary nonpolyposis colorectal cancer and endometrial cancer." (PMID 29641532, 2018). "Data on prevalence of heterogenic MSH6 expression in iCCA are lacking to date, but it was described to be present in other neoplasms such as colorectal and endometrial carcinomas." (PMID 28146430, 2017). "The limitation of this study is the lack of our own clinical samples of endometrial cancer to validate the results, especially the need to verify the relationship between MSH6 and immune infiltration, immune checkpoint expression and ICIs treatment responsiveness." (PMID 38390329, 2024). "The proportion of MSH6/PMS2, where the non-endometrioid type with poor prognosis is found more frequently, appears to be high in endometrial cancer LS." (PMID 35884469, 2022).
ovarian carcinoma (103 papers, 1999 to 2026). A malignant neoplasm originating from the surface ovarian epithelium. "The uptake of BSO was slightly lower and followed the same pattern, although path_MSH6 carriers have a very low risk for ovarian cancer before 50 years of age." (PMID 33743481, 2021). "A number of recent studies have reported that MSH6 gene expression is associated with an increased risk of breast or ovarian cancer." (PMID 34941572, 2021). "In the group with pathogenic variants in MSH6, ovarian cancer was noted in around 11.5% versus 4% in the MLH1 group." (PMID 30386444, 2018). "The two PMS2 mutations are associated with a significantly increased risk of endometrial, colorectal and ovarian cancer, although the overall cancer risks are lower than for the MSH6 mutation." (PMID 28466842, 2017). "Similar to previous studies, our research also indicated that MSH6 may be a susceptibility gene for breast cancer or ovarian cancer, and the expression of MSH6 gene may cause poor survival prognosis in these two cancer patients." (PMID 34941572, 2021). "On the other hand, ATM and PALB2 are considered moderate penetrance genes in breast and ovarian cancer, and MSH6, PMS2, and EPCAM are considered moderate penetrance genes in LS CRC." (PMID 38201484, 2023).
ovarian carcinoma (continued). "Other genes with a notable hysterectomy risk (at p < 1e−9) were MSH6 (OR = 3.3; p = 1.9e−20) and BRCA1 (OR = 1.9; p = 9.5e−10), most likely explained by susceptibility to endometrial and ovarian cancers, respectively." (PMID 36773604, 2023). "The MSH6 total protein expression level in the primary tumor tissues of colon cancer, breast cancer, ovarian cancer, LUAD, and clear cell RCC was all higher than that of normal tissues (all P<0.001)." (PMID 34941572, 2021). "PLSD reported a cumulative incidence of endometrial and ovarian cancer at 75 years of 37% and 11% for path_MLH1 carriers, 49% and 17% for path_MHS2 carriers and 41% and 11% for path_MSH6 carriers, respectively." (PMID 32708519, 2020). "MLH1 carriers had an elevated proportion of gastrointestinal cancers (gastric, small bowel, pancreas), while MSH6 carriers had more ovarian cancer than expected." (PMID 30386444, 2018). "In contrast, MLH1 carriers show an increased proportion of gastrointestinal cancers and MSH6 carriers of ovarian cancer." (PMID 30386444, 2018). "We discover a translocation disrupting MLH1 and three mutations in MSH6 and PMS2 that increase endometrial, colorectal, brain and ovarian cancer risk." (PMID 28466842, 2017). "Breast and prostate cancer were observed in 23% of the MSH6 families, while ovarian cancer was observed in 17% of the families." (PMID 20487569, 2010). "Apart from BRCA1, BRCA2 and MSH6, no clearly pathogenic variant was identified in other established ovarian cancer genes tested." (PMID 37013556, 2023). "Using the CPTAC dataset, we first explored the molecular mechanism of MSH6 protein in breast cancer, colon cancer, lung adenocarcinoma, clear cell renal cell carcinoma, ovarian cancer, and uterine corpus endometrial carcinoma from the perspective of total protein and phosphoprotein." (PMID 34941572, 2021).
ovarian carcinoma (continued). "Similarly, the S830 locus within the MutS_III domain of MSH6 also indicates a higher phosphorylation level in primary tumor tissues of breast cancer, ovarian cancer colon cancer and UCEC in comparison with normal tissues (all P<0.05)." (PMID 34941572, 2021). "Two genes (VCAN, MSH6) are common in endometrial, breast and ovarian cancers." (PMID 31205821, 2019). "Among seven MMR genes, high mRNA levels of MSH6, MLH1 and PMS2 were significantly associated with a better overall survival for all ovarian cancer patients treated with platinum-based chemotherapy, especially in late-stage and poor-differentiated ovarian cancer patients." (PMID 29063235, 2018). "Increased MSH6 and MLH1 mRNA levels were associated with a better OS in stage III + IV ovarian cancer patients, high mRNA levels of PMS2 implied an improved OS either in stage I + II or stage III + IV ovarian cancer patients." (PMID 29063235, 2018). "In MSH6 gene mutation carriers, CRC and ovarian cancer risks are lower." (PMID 23164213, 2012). "In addition to 13.7% of deleterious germline BRCA1/BRCA2 carriers, we identified 7.4% additional patients with pathogenic germline variants in other genes predisposing for ovarian cancer, namely RAD51C, RAD51D, and MSH6, representing 35% of all pathogenic germline variants." (PMID 33008098, 2020). "Our results showed that high mRNA levels of MSH6, MLH1, and PMS2 were associated with a favorable OS in ovarian cancer, suggesting these MMR genes may serve as potential positive prognostic indicators in ovarian cancer patients treated with platinum-based chemotherapy." (PMID 29063235, 2018). "In contrast, in comparison with normal tissues, the S261 locus and S137 locus of MSH6 demonstrated a lower phosphorylation level of primary tumor tissues of clear cell RCC and ovarian cancer, respectively (all P <0.05)." (PMID 34941572, 2021). "PV in 10 PDAC patients with multiple primary tumors affected 3 × BRCA1 and 4 × BRCA2 (all had also developed breast and/or ovarian cancer), 1 × PMS2 and 1 × MLH1/MSH6 (both developed colon cancer), and 1 × CDKN2A (diagnosed with melanoma)." (PMID 34503238, 2021). "The CPTAC dataset was applied to analyze the differences in the phosphorylation levels of MSH6 in normal and primary tumor tissues of six different tumors (colon cancer, breast cancer, LUAD, ovarian cancer, clear cell RCC and UCEC)." (PMID 34941572, 2021). "The mutations p.Asp95Asn in NBN and p.Lys425Arg in POLE segregated with both breast and ovarian cancer cases; the VUS in MSH6 p.Ser144Ile was identified in the two cases of breast cancer, one of them bilateral, in an HNPCC family." (PMID 32522261, 2020). "Nevertheless, we failed to observe the correlation between MSH6 expression and the survival prognosis of patients with breast or ovarian cancer in the TCGA-BRCA/OV cohort." (PMID 34941572, 2021).
ovarian carcinoma (continued). "Furthermore, we also observed a correlation between MSH6 high expression and poor prognosis of OS, PFS and PPS in ovarian cancer cases." (PMID 34941572, 2021). "We identified in one patient with both endometrial and ovarian cancer a MSH6 germline inframe deletion, which is not described in the literature at the time of writing." (PMID 33008098, 2020). "While high levels of MLH1 were associated with a better OS in grade III ovarian cancers and increased mRNA expression of PMS2 was positively correlated with OS in grade II ovarian cancer, MSH6 mRNA expression was a favorable predictor of OS both in grade II and grade III ovarian cancer patients." (PMID 29063235, 2018). "In addition, our study showed the expression of MSH6, MLH1 and PMS2 gene exerted positive influences on OS of late-stage and poor-differentiated ovarian cancer patients, but not of early stage and well-differentiated ovarian cancer patients." (PMID 29063235, 2018).